TAP1 (transporter 1, ATP binding cassette subfamily B member)
Diseases named in the same sentence as TAP1 in open-access papers (continued):
Sharing a sentence is not in itself a finding about the gene and the disease.
tumor (continued). "Beyond its high in vivo stability, [125I]TAP1 also had preferable biodistribution in normal mice, and moderate tumor accumulation that partly corresponded to the FABP4 in vivo expression profile." (PMID 24732569, 2014). "OVA peptide SIINFEKL presented by RMA-S, a Tap-1−/− H2b tumor cell line, is a strong stimulus for OT1 CTL." (PMID 23840635, 2013). "Recent reports have demonstrated the multifunctional deficiencies of components of the MHC class I antigen-presentation pathway including LMP2 and TAP-1 in tumor cells." (PMID 21437229, 2011). "It has been shown that HDACi treatment can activate the proteasomal components (LMP2, LMP7), transporters associated with antigen processing (TAP1, TAP2) and the TAP-associated glycoprotein (tapasin) gene in tumor cells." (PMID 24212778, 2011). "The loss or dysfunction of molecules involved in antigen processing and presentation (such as TAP1, TAP2, LMP2, LMP7 and Tapasin) via the class I pathway contributes to deficient class I expression in several tumor types." (PMID 24212778, 2011). "One such T-cell clone recognizes an ER-localized-Lass5-protein-derived antigen that is presented exclusively by RMA-S and other TAP1 or TAP2 deficient cells and protects mice from RMA-S tumor challenge." (PMID 19629186, 2009). "This study demonstrates that B7.1 and TAP1 co-expression in TAP-negative CMT.64 cells renders tumor cells potent immunogens able to effectively induce a CD8+ T-cell mediated immune response against TAP-negative tumors." (PMID 19629186, 2009). "Different capacities for antigen presentation are also observed between TAP-negative and TAP1-positive tumor cells." (PMID 19629186, 2009). "In summary, B7.1 and TAP1 co-expression in TAP-negative tumor cells provides two major advantages for induction of a T-cell mediated antitumor immune response." (PMID 19629186, 2009). "Results of this experiment demonstrate that a substantial decrease in tumorigenicity is mediated by expression of B7.1 together with TAP1 molecules in CMT.64 tumor cells." (PMID 19629186, 2009). "Taken together, we conclude that effective vaccination with virally infected TAP-negative cells requires both B7.1 and TAP1 co-expression in the tumor cells." (PMID 19629186, 2009). "TAP1 expression affords tumor cells the ability to efficiently present TAP-independent antigen(s) while B7.1 expression in tumor cells decreases the threshold for priming of TAP-independent antigen specific T cells." (PMID 19629186, 2009). "B7.1 and TAP1 co-expression in tumor cells significantly decreases their tumorigenicity while B7.1 expression alone in the cells has no change." (PMID 19629186, 2009). "Our results further show that immunization with either TAP1-expressing or TAP-negative tumor cells that express B7.1 can elicit an effective T-cell mediated immune response against TAP-negative tumor challenge." (PMID 19629186, 2009). "At the low dose of tumor immunization, only B7.1 and TAP1 co-expressing cells provided protective immunity." (PMID 19629186, 2009). "Increased survival of mice immunized with γ-irradiated MHC-I proficient tumor (CMT.TAP1,2/Kb) cells is likely due to this mechanism." (PMID 18769733, 2008). "For in vitro experiments, γ-irradiated CMT.64 and CMT.TAP1,2/Kb were used to immunize mice and the two immunized splenocyte populations were compared for tumor-antigen recognition using a 51Cr-release assay." (PMID 18769733, 2008). "Whether tumor recurrence is related to mutations in MKNK1, POLE, RET, RTEL1, RUNX1T1, TAP1 still requires further research for validation." (PMID 40901169, 2025). "Mutant TAP1 has been reported to influence MHC-I function in tumor surveillance." (PMID 40535120, 2025). "For instance, Transporter Associated with Antigen Processing 1 (TAP1)/ATP-Binding Cassette Subfamily B Member 2 (ABCB2) deficiency has been linked to increased CD8+ T cells and decreased tumor-associated neutrophils and CD4+ regulatory T cells, enhancing anti-PD-1 responses." (PMID 40445912, 2025).
tumor (continued). "Loss of TAP1 and TAP2 further reduces tumour immunogenicity by limiting peptide loading onto MHC-I." (PMID 41179304, 2025). "The expression of TAP1 was shown to be widely expressed in the WT tumor tissue treated with PBS." (PMID 39388288, 2024). "We observed that, compared with Map3k1-WT, Map3k1-mut could significantly promote Tap1/2 mRNA degradation in tumor cells." (PMID 39531335, 2024). "To further determine whether Map3k1 regulated surface MHC-I expression via regulation of Tap1/2 expression, we performed a rescue assay by overexpressing Tap1/2 in Map3k1-mut tumor cells." (PMID 39531335, 2024). "We then tested the stability of Tap1/2 mRNA in tumor cells in the coculture system." (PMID 39531335, 2024). "Similarly, the expression of genes related to antigen processing and presentation such as Tap1, Tap2, B2m, and Psmb9, was also upregulated in tumors from hsBCL9z96-treated CT26 tumor-bearing mice and MC38 tumor-bearing Bcl9/Bcl9l deficiency mice." (PMID 38811552, 2024). "In addition, we performed an RNA immunoprecipitation (RIP) assay to compare the ability of DDX17 to bind Tap1/2 mRNAs in Map3k1-WT and Map3k1-Mut tumor cells in the coculture system." (PMID 39531335, 2024). "After annexin V/propidium iodide staining, the number of annexin V-positive cells increased significantly after TAP1 knockdown, indicating that silencing TAP1 could induce tumor cell apoptosis." (PMID 36774490, 2023). "Overall, these results suggest that the effect of TAP1 gene expression on the tumor microenvironment may have an important role in the occurrence, development, metastasis, and immune response of UVM." (PMID 36774490, 2023). "In addition to immunotherapy, previous studies have reported success in increasing tumor-specific immune responses by restoration of TAP1 expression via a TAP1 expressing adenovirus." (PMID 36759763, 2023). "Hence, TAP1 expression levels in tumor tissue represents a summation of that in all types of cells present in the tumor." (PMID 36759763, 2023). "We speculated that BLCA and SKCM patients with higher TAP1 expression might indicate higher lymphocyte infiltration in tumors, which usually results the tumor cells more vulnerable under the ICI therapy condition." (PMID 36759763, 2023). "To link the prognostic role and single cell expression of TAP1 in cancers, we speculated that the cancers with better prognosis and high TAP1 expression also have high tumor infiltrating lymphocyte populations." (PMID 36759763, 2023). "Currently the TAP1 is closely related to immune microenvironment, which might exert an influence depending on immune cells, or tumor microenvironment." (PMID 36419887, 2022). "Based on tumor grade, TAP1 expression was positively correlated with advanced cancer." (PMID 36419887, 2022). "To simulate the immune evasion mechanism of HLA-I downregulation in tumor cells in vitro, we first knocked out TAP1 and TAP2 simultaneously and knocked out B2M genes in several solid tumor cells (A375, A549 and 786-O) using CRISPR/Cas9 technology, respectively." (PMID 36612246, 2022). "In view of the role of TAP1 in tumor drug resistance, we also predicted the drug AFA464 that may be effective against high TAP1 expression." (PMID 36419887, 2022). "have indicated that TAP1 down-regulation might lead to the presentation of empty HLA molecules, which means that tumor cells could evade recognition from NK cells by expressing HLA molecules on their surface." (PMID 36419887, 2022). "We analyzed the relationship between the high expression of TAP1 and tumor immune infiltration." (PMID 36419887, 2022). "This discrepancy could be explained by other influences of TAP1 on tumor development independently of drug efflux." (PMID 35806187, 2022). "The high expression of TAP1 promotes tumor migration and metastasis in vivo and in vitro." (PMID 36419887, 2022).
tumor (continued). "Subsequently, we analyzed SQLE expression and its association with biomarkers of MHC (B2M, HLA-B, HLA-C, TAP1, and TAP2), dendritic cells (BATF3), macrophages (CD68 and IL1A), type-I anti-tumor responses (CD8A and GZMB), and cell proliferation (MKI67) in 178 PAAD tissues." (PMID 35720314, 2022). "The consideration of microenvironment for tumor seems essential regarding the expression of a gene as TAP1 as its regulation may be determined by proteins like STAT1 and IRF1." (PMID 34047812, 2021). "The anti-tumor effect of the S-540956-adjuvanted vaccine was significantly reduced in Tap1-/- mice." (PMID 35003132, 2021). "We found that for BRCA, LIHC, and LUAD, all had a high expression of TAP1 gene for stage 2 carcinomas, indicating that that TAP1 might be present in an increased amount in stage 2 tumor in various cancers." (PMID 34047812, 2021). "We directly explained the significant correlation between TAP1 and tumor immune cell infiltration in OC as well as immune scores, which suggested that TAP1 could influence the abundance of TIICs in OC." (PMID 34957213, 2021). "Recent studies showed that TAP1 was closely related to a variety of tumors, which may be related to tumor cells evading the recognition of cytotoxic T cells by shutting down peptide delivery." (PMID 34957213, 2021). "Any defect in the TAP1 gene resulting in inadequate tumor tracking." (PMID 34047812, 2021). "Though low TAP1 expression is related with tumor development and alteration of TAP1 may lead to evasion of cytotoxic T-cell killing of some cancer cells, but studies are also present about downregulating TAP1 as a way to promote neoantigens as tumor immunity." (PMID 34047812, 2021). "In addition, we examined the expression of TAP1 protein in OC and CC cell lines by using western blot assays and its role in tumor metastasis in vivo and vitro." (PMID 34957213, 2021). "Therefore, we used the median TAP1 mRNA level to divide the mixed group of 42 tumor-free samples into TAP1-low and TAP1-high groups." (PMID 32867395, 2020). "Our results, which show that TAP1 levels in tumor-free tongue contralateral to the SCCOT correlate with survival, are an important contribution to early diagnostics and follow up of SCCOT, improving our overall understanding of this complicated and severe disease." (PMID 32867395, 2020). "Whereas levels of TAP2 were almost unchanged in the 21 tumor-free samples studied here, the group with TAP1 mRNA levels below the median showed significantly better overall and disease-free survival when considering age, sex, cytolytic activity, and tumor stage." (PMID 32867395, 2020). "Whereas low levels of TAP1 are an indicator of better survival, increased levels could serve as a sign of malignancy in tumor-free tissue contralateral to a treated SCCOT." (PMID 32867395, 2020). "Presentation of tumor associated antigens by MHC-I molecule is regulated by the transcription of antigen processing machinery (APM) genes involving low molecular mass proteins LMP-2 and LMP-7 and transporters associated with antigen processing TAP-1 and TAP-2." (PMID 31737100, 2019). "The authors showed that such fusion proteins are endocytosed via binding to the chemokine receptor and are delivered to the cytosol for proteasomal processing, resulting in their loading on MHC class I molecules in a TAP-1-dependent manner, leading to potent tumor control." (PMID 30863405, 2019). "The tumor specimens represented in the TMAs expressed the TAP1 and TAP2 subunits at various levels." (PMID 29091951, 2017). "A possible explanation for the strong anti-tumorigenic effect of IFNα could therefore be the enhanced cell surface presentation of tumor specific peptides via MHC class I molecules as a result from upregulation of TAP1 expression." (PMID 26735690, 2016).
tumor (continued). "To test whether this stimulatory activity of IFNα is also seen in the tumor tissue itself we excised tumors from IFNα-treated and control mice three days after the final injection of IFNα (day +11) and analyzed TAP1 mRNA by qRT-PCR in tumor tissue." (PMID 26735690, 2016). "In the minimal tumor tissue present in IFNα-treated mice up to 5-fold higher TAP1 mRNA levels could be detected in comparison to TAP1 mRNA levels in tumors of the untreated control group (p = 0.068)." (PMID 26735690, 2016). "Thus, [125I]TAP1 would be a unique probe that has the potential to evaluate tumor stromal functions." (PMID 24732569, 2014). "As such, [125I]TAP1 could have applications for clarifying the relationship between tumor malignancy and the function of FABP4 in such tumors." (PMID 24732569, 2014). "[125I]TAP1 biodistribution was also evaluated in tumor-bearing mice." (PMID 24732569, 2014). "A possible role for the IFN-γ-responsive gene TAP-1 in tumor recognition was reported." (PMID 21437229, 2011). "However, both B7.1-expressing and B7.1 and TAP1 co-expressing cells dramatically increased the capacity for generation of protective immunities at the high dose of tumor immunization." (PMID 19629186, 2009). "This indicates that TAP1 expression plays a critical role in enhancing T-cell priming which suggests that TAP1 expression may facilitate efficient presentation of TAP-independent tumor antigens." (PMID 19629186, 2009). "Results suggest that at the high dose of immunization, B7.1 and TAP1 co-expression or B7.1 expression alone renders tumor cells potent immunogens, while at low dose immunization, potent immunogenicity requires tumor cells co-expressing both TAP1 and B7.1 molecules." (PMID 19629186, 2009). "In addition, inoculation with live tumor cells transfected with several different gene(s) revealed that only B7.1- and TAP1-coexpressing tumor cells significantly decreased tumorigenicity." (PMID 19629186, 2009). "Next, we performed in vitro and in vivo experiments to determine whether the TAP and MHC-I proficient CMT.TAP1,2/Kb was able to induce tumor-antigen specific immunity." (PMID 18769733, 2008). "In addition, the tumor-immune correlation analysis demonstrated that PHF8 expression was strongly negatively associated with the levels of MHC class I genes including B2M, HLA-A/B/C, TAP1/2 as well as chemokines such as CCL5 and CXCL10." (PMID 40001243, 2025). "Therefore, disruption in TAP1/2 proteins in malignant cells could affect the levels of surface peptide HLA-complexes and reduce the tumor recognition by cognate effector tumor antigen-specific T-cells." (PMID 40091029, 2025). "Hence, the reasons for aberrant TAP1 expression in tumor tissue remain to be determined." (PMID 36759763, 2023). "However, as the tumor progresses, the expression level of TAP1 is increased." (PMID 36419887, 2022). "On the other hand, recently, researchers have illustrated that the silent TAP1 induced the presentation of a TAP-independent peptide in human tumor cells, and thereby enhanced the effectiveness of immune potentiating therapies, which is additionally considered associated with tumor drug resistance." (PMID 36419887, 2022). "However, the mechanism of TAP1 affecting tumor biological behavior varies among different tumors." (PMID 36419887, 2022). "Moreover, knockdown of TAP1 in MEKi-resistant tumor significantly decreased tumor growth in vivo." (PMID 35806187, 2022). "Overall, we found that TAP1 could possibly affect the tumor immunotherapy." (PMID 34957213, 2021). "Therefore, we speculated that DNMT1 changed the methylation status of TAP1 and affected the infiltration of tumor immune cells thereby changing the prognosis of OC, which was worthy of further verification." (PMID 34957213, 2021).
tumor (continued). "Whereas increased cytolytic activity could be part of the inflammatory response in the tumor vicinity and thus play a protective role, the importance of decreased levels of TAP1 is harder to explain as it is not well known how its expression is regulated under normal conditions." (PMID 32867395, 2020). "Finally, dividing patients into TAP1-high and TAP1-low groups according to the median TAP1 level in tumor-free samples demonstrated that patients with lower TAP1 mRNA levels in tumor-free samples had better overall (p = 0.003) and disease-free survival (p = 0.002)." (PMID 32867395, 2020). "Even though TAP-independent antigens can be presented by TAP1-positive or TAP-negative tumor cells, failure of the cells to efficiently induce a large population of tumor-antigen specific CD8+ T-cell effectors may be a major reason limiting efficacy of antitumor immunity." (PMID 19629186, 2009). "IRF1, IRF9 and STAT1 in lymphoid cells of C1 participated in anti-tumor immune response by impacting target genes CD8A, HLA-A/E, TAP1 and PD-1." (PMID 42074110, 2026). "Concurrently, GNL3 functions as a corepressor of immune-responsive genes such as CXCL10 and TAP1 via class I histone deacetylases (HDACs), thereby facilitating CD8+ T cell elimination and establishing an immunosuppressive tumor microenvironment." (PMID 41772945, 2026). "Specifically, EZH2 inhibition upregulates TAP1, restores MHC I expression on the tumor cell surface, and increases the presentation of antigenic peptides, making the tumor more likely to be recognized and targeted by the immune system." (PMID 41220942, 2025). "SAHA also significantly upregulates the expression of four antigen presentation-related proteins—TAP1, TAP2, LMP2, and LMP7—in U251 and GL261 cells, enhancing immune cell recognition of tumor cells." (PMID 40573881, 2025). "The immune escape from T cells caused by the knockout of genes IFN-γ signaling pathway (JAK1, JAK2, Ifngr2) and antigen presentation pathway (TAP1, TAP2, B2M) promotes tumor vulnerability to NK cells." (PMID 40191187, 2025). "In contrast, aT-sEVs downregulated the expression of PD-L1, TAP1, HLA-A, HLA-B, HLA-C and ICAM-1 in tumour cells." (PMID 38719909, 2024). "Several antigen presentation genes, such as Tap1 and CD74 and some regulators involved in tumor cell immunogenicity, such as Irf1, Icam1 and CD40 were also upregulated by Mi-2β knockout in vitro." (PMID 38461299, 2024). "Mechanistically, MAP3K1 mutation suppressed MHC-I–mediated tumor antigen presentation through promoting the degradation of antigen peptide transporter 1/2 (TAP1/2) mRNA, thereby driving tumor immune escape." (PMID 39531335, 2024). "TAP1, TAP2, TAPBP, and β2-microglobulin (B2M) are critical proteins involved in the class I MHC antigen presentation process in virus-infected or tumor cells." (PMID 39388288, 2024). "VC enhanced the expression of MHC I antigen-presenting genes TAP1 and TAPBP in WT B16-OVA tumor cells." (PMID 39388288, 2024). "With the help of TAP1 and TAP2, CD8+ T cell can identify MHC-I molecules on the exterior of tumor cells, resulting in the destruction of tumor cells." (PMID 39132149, 2024). "The findings from the ceRNA network further proved that TAP1 is essential for UVM initiation, progression, metastasis, and the tumor microenvironment." (PMID 36774490, 2023). "Western blot experiments further showed that the expression levels of the tumor metastasis markers, matrix metallopeptidase 9 (MMP9) and MMP2, were decreased significantly in C918 cells after TAP1 silencing." (PMID 36774490, 2023). "STING agonists are verified to induce tumor cells apoptosis, allowing the leak of antigen-presenting molecules such as TAP1, TAP2, and MHC-I via the upregulation of IFN to further cross-prime anti-tumor T-cells and enhance immunosurveillance of tumors." (PMID 37122745, 2023).